RN7SL630P (RNA, 7SL, cytoplasmic 630, pseudogene)
Gene: Miscellaneous RNA gene on chromosome 12 (93,831,076 to 93,831,372, forward strand). Ensembl gene ENSG00000264978.
Homologues: Orthologues: chimpanzee Metazoa_SRP (99% identical), macaque Metazoa_SRP (96% identical). Paralogues in human: RN7SL1 (86% identical), RN7SL3 (86% identical), RN7SL2 (85% identical), RN7SL45P (84% identical), RN7SL664P (82% identical), RN7SL597P (82% identical), RN7SL709P (82% identical), RN7SL783P (82% identical), RN7SL230P (82% identical), RN7SL444P (82% identical), RN7SL543P (82% identical), RN7SL769P (82% identical), and 706 more.